EGLN1 (egl-9 family hypoxia inducible factor 1)
Description:
Cellular oxygen sensor that catalyzes, under normoxic conditions, the post-translational formation of 4-hydroxyproline in hypoxia-inducible factor (HIF) alpha proteins. Hydroxylates a specific proline found in each of the oxygen-dependent degradation (ODD) domains (N-terminal, NODD, and C-terminal, CODD) of HIF1A. Also hydroxylates HIF2A. Has a preference for the CODD site for both HIF1A and HIF1B. Hydroxylated HIFs are then targeted for proteasomal degradation via the von Hippel-Lindau ubiquitination complex. Under hypoxic conditions, the hydroxylation reaction is attenuated allowing HIFs to escape degradation resulting in their translocation to the nucleus, heterodimerization with HIF1B, and increased expression of hypoxy-inducible genes. EGLN1 is the most important isozyme under normoxia and, through regulating the stability of HIF1, involved in various hypoxia-influenced processes such as angiogenesis in retinal and cardiac functionality. Target proteins are preferentially recognized via a LXXLAP motif.
Synonyms: HIF-PH2; HPH-2; PHD2; C1orf12; SM-20; ZMYND6; HIFPH2; ECYT3; HALAH; HPH2; SM20
Tractability: Small molecule: an approved drug acts on it; a structure with a bound ligand is known; a high-quality ligand is known; it belongs to a druggable protein family. PROTAC: ubiquitination databases record sites on it; its protein half-life has been measured; a small molecule that binds it is known.
Target class: Enzyme; Oxidoreductase
Chemical probes: IOX2 (high quality)
Gene: Protein-coding gene on chromosome 1 (231,363,751 to 231,422,744, reverse strand). Ensembl gene ENSG00000135766.
Subcellular location: Cytoplasm; Nucleus
Subcellular location (Human Protein Atlas): Cytosol; Vesicles
Pathways (Reactome):
Cellular responses to stimuli: Oxygen-dependent proline hydroxylation of Hypoxia-inducible Factor Alpha
Gene Ontology:
Molecular function: 2-oxoglutarate-dependent dioxygenase activity; ferrous iron binding; hypoxia-inducible factor-proline dioxygenase activity; protein binding; enzyme binding; enzyme inhibitor activity; peptidyl-proline 4-dioxygenase activity; peptidyl-proline dioxygenase activity; iron ion binding; L-ascorbic acid binding; oxidoreductase activity, acting on paired donors, with incorporation or reduction of molecular oxygen
Biological process: intracellular oxygen homeostasis; negative regulation of hypoxia-inducible factor-1alpha signaling pathway; response to hypoxia; response to nitric oxide; cellular response to hypoxia; regulation of angiogenesis; regulation of neuron apoptotic process; intracellular iron ion homeostasis; positive regulation of transcription by RNA polymerase II; regulation of modification of postsynaptic structure; regulation protein catabolic process at postsynapse
Cellular component: cytoplasm; cytosol; nucleus; glutamatergic synapse; postsynaptic density
Genetic constraint (gnomAD): Loss-of-function variants: 17 observed, 34.49 expected, observed/expected ratio (o/e) 0.49, 90% interval 0.34 to 0.74. The synonymous counts are far from expectation, so gnomAD's model fits this gene poorly and the ratio says little. Missense variants: 477 observed, 534.92 expected, observed/expected ratio (o/e) 0.89, 90% interval 0.83 to 0.96. Synonymous variants: 283 observed, 229.48 expected, observed/expected ratio (o/e) 1.23, 90% interval 1.12 to 1.36.
Homologues: Orthologues: chimpanzee EGLN1 (99% identical), macaque EGLN1 (98% identical), dog EGLN1 (89% identical), pig EGLN1 (88% identical), rabbit EGLN1 (88% identical), mouse Egln1 (77% identical), zebrafish egln1b (58% identical), zebrafish egln1a (55% identical), tropical clawed frog egln1 (53% identical), Caenorhabditis elegans egl-9 (32% identical), zebrafish egln1b (32% identical). Paralogues in human: EGLN2 (42% identical), EGLN3 (34% identical).
Diseases named in the same sentence as EGLN1 in open-access papers:
EGLN1 is named in the same sentence as 169 diseases in open-access papers, as found by Europe PMC text mining. Sharing a sentence is not in itself a finding about the gene and the disease. The quoted sentences say what the papers report.
erythrocytosis (41 papers, 2010 to 2025). "Conversely, a recent characterization of genetic variants in the EGLN1 gene, identified in a cohort of European erythrocytosis patients, revealed a link between this protein and erythrocytosis." (PMID 39859474, 2025). "Genetic testing eventually confirmed that his son was positive for an EGLN1 gene variant associated with familial erythrocytosis." (PMID 40627222, 2025). "Up to now, 96 different EGLN1 genetic variants have been reported in patients with erythrocytosis, from whom 36 were classified as pathogenic or likely pathogenic, and in almost all cases, patients were heterozygous." (PMID 39309680, 2024). "Erythrocytosis associated with a PHD2 (also known as EGLN1) mutation was described across generations in multiple members of a family." (PMID 34440325, 2021). "The association of hereditary erythrocytosis with mutations of the PHD2 gene (also known as the EGLN1 gene) has been previously reported." (PMID 27034858, 2016). "Carrying the rs2790859 SNP in EGLN1, which is involved in the hypoxia response, has been suggested as a risk factor for polycythemia in modern Tibetan highlanders living in Tsarang, indicating a potential association between genotype and disease susceptibility." (PMID 39407294, 2024). "The patient harboring the H374R mutant originally presented with erythrocytosis, but a tumor matching the characteristics of a paraganglioma was later diagnosis at 43 years old This individual displayed loss of the remaining wild-type EGLN1 allele." (PMID 36040300, 2022). "Germline and somatic mutations in genes involved in the hypoxia-sensing pathway, including Von Hippel-Lindau (VHL) and Egl-9 homolog 1 (EGLN1; also known as prolyl hydroxylase domain-containing protein 2 [PHD2]), have been described in neuroendocrine tumor syndromes associated with polycythemia." (PMID 32235007, 2020). "In support of the hypothesis that hypermethylation of EGLN1 contributes to the excessive production of red blood cells in CMS, EGLN1 inactivation in mice results in an overproduction of erythropoietin and polycythemia, and familial polycythemia in humans has been linked to EGLN1 mutations." (PMID 30781443, 2019). "Four types of erythrocytosis are known to be caused by mutations in genes encoding key players of oxygen-sensing signaling, namely VHL (ECYT2), EGLN1/PHD2 (ECYT3), EPAS1/HIF2α (ECYT4) and EPO (ECYT5)." (PMID 34440324, 2021). "This could suggest a connection between EPAS1, EGLN1, and Hb production, especially based on what we know about Tibetan and Andean populations whose genetic variation in both genes has been implicated in protecting individuals from erythrocytosis/polycythemia, resulting from living at high-altitude." (PMID 30631144, 2019). "In 2008, a germ-line mutation in EGLN1, also called PHD2, was reported in a patient with erythrocytosis and recurrent para-aortic PGL." (PMID 26347711, 2015). "EGLN1 and EPAS1 play an important role in determining the variability in the response to hypobaric hypoxia at altitude and have been linked to the development of polycythemia and associated abnormalities." (PMID 36835089, 2023). "We present a long-term survey of pediatric liver recipients, evaluating prevalence, outcome and the main potential causes of erythrocytosis, including a comprehensive mutational analysis of commonly related genes (mutations of HBB and HBA, JAK2, EPOR, VHL, EPAS1 and EGLN1)." (PMID 32546701, 2020). "Contrastingly, Provenzano and colleagues have recently described a novel germline EGLN1 gene variant in a patient with metastatic PCC and chronic myeloid leukemia (CML) in the absence of polycythemia." (PMID 36699028, 2022). "This discovery could be significant for certain pathologies where the erythropoietic effect is not desirable, such as secondary congenital erythrocytosis where disease develops due to mutations in genes regulating Epo such as VHL, EGLN1, EPAS1, or EPO." (PMID 35682566, 2022).
erythrocytosis (continued). "Preliminary epigenetic investigation of specific sites in the EGLN1 region in Andeans suggests distinct levels of methylation between Andeans with and without excessive erythrocytosis, and recent studies show variants at this locus are associated with exercise capacity in Andeans." (PMID 32849780, 2020).
pulmonary hypertension (19 papers, 2016 to 2024). Increased pressure within the pulmonary circulation due to lung or heart disorder. "Previously, our lab found that endothelia-specific knockout of Egln1, encoding prolyl 4-hydroxylase-2 (PHD2), induced spontaneous pulmonary hypertension (PH)." (PMID 38974505, 2024). "Increased erythropoietin (EPO) in patients with familial/idiopathic erythrocytosis and pulmonary hypertension is associated with mutations in EGLN1 (PHD2) and EPAS1 (HIF2α); a drug inhibiting HIF2α activity is used for clear cell renal cell carcinoma (ccRCC) treatment." (PMID 37449559, 2023). "In this study, we employed the first severe pulmonary hypertension (PH) mouse model, Egln1Tie2Cre (Tie2Cre-mediated disruption of Egln1) mice, to identify the novel autocrine signaling mediating the pulmonary vascular endothelial cell (PVEC) proliferation and the pathogenesis of PAH." (PMID 33804745, 2021).
paraganglioma (15 papers, 2014 to 2025). A benign or malignant neoplasm arising from paraganglia located along the sympathetic or parasympathetic nerves. "Additional research is required to disclose the role of EGLN1 mutations in paragangliomas." (PMID 24899893, 2014). "Recently, other genes (TMEM127, MAX, HIF2A, EGLN1, KIF1B, H-RAS) have been added to the group of susceptibility genes involved in the development of paragangliomas/PHEO." (PMID 26084817, 2015). "More recently, the TMEM127, MAX, HIF2A, EGLN1, KIF1B, and H-RAS complete the list of susceptibility genes implicated in the development of paragangliomas/pheochromocytomas." (PMID 24899893, 2014). "Mutations in some genes have been found only in single patients or families (e.g., MEN1, EGLN1, EGLN2, MDH2, IDH1, BAP1, BRAF); therefore, their role in the formation of paragangliomas/pheochromocytomas cannot be reliably confirmed." (PMID 28187001, 2017).
melanoma (14 papers, 2013 to 2025). A malignant, usually aggressive tumor composed of atypical, neoplastic melanocytes. "Many of the identified fitness genes such as NFATC2 and EGLN1 have an as yet undetermined role in melanoma biology." (PMID 32767816, 2021).
pheochromocytoma (14 papers, 2008 to 2024). "Inactivating germline mutations in EGLN1 have been identified to cause erythrocytosis and deregulation of EGLN3 has been linked to the development of pheochromocytoma, a neuroendocrine tumor of the adrenal glands." (PMID 18773095, 2008).
lung carcinoma (10 papers, 2017 to 2024). "We evaluated the association between lung cancer and Tibetan-specific EGLN1 and EPAS1 genetic variants." (PMID 28036300, 2017). "We observed a significant association between the selected Tibetan EGLN1/PHD2 haplotype and lung cancer (p=0.0012 for D4E, p=0.0002 for C127S), corresponding to a two-fold increase in lung cancer risk." (PMID 28036300, 2017). "In our case-control study, we evaluated association between lung cancer and Tibetan-specific evolutionary selected EGLN1 variants, EGLN1D4E and EGLN1C127S and ten EPAS1 SNPs with strong evidence of positive selection." (PMID 28036300, 2017). "We found that the adaptive Tibetan EGLN1 haplotype was associated with a two-fold increase in the risk of lung cancer (p=0.0012 for D4E, p=0.0002 for C127S)." (PMID 28036300, 2017). "High expression of FSP1, EGLN1 and STRYK1 was found to be associated with greater ferroptosis resistance in lung cancer cells." (PMID 34277151, 2021). "Our data cannot address the specific role of EGLN1 and EPAS1 genetic variants in lung cancer initiation, progression, or survival." (PMID 28036300, 2017). "However, we conclude that high-altitude adapted Tibetan variants in the EGLN1 and possibly EPAS1 regions are associated with the modified lung cancer risk, and that the role of these Tibetan evolutionary selected haplotypes needs to be further elucidated." (PMID 28036300, 2017). "A previous study indicated that EGLN1 could act as an oncogene by inducing LSH expression, which inhibits ferroptosis in lung cancer." (PMID 34277151, 2021).
colorectal cancer (8 papers, 2010 to 2024). A primary or metastatic malignant neoplasm that affects the colon or rectum. "Similar to our results, other studies indicate a decreased EGLN1 mRNA level in non-small-cell lung cancer compared to normal lung tissues and colorectal cancer." (PMID 38928200, 2024). "Previous studies have shown that EGLN1 expression is closely related to the occurrence and prognosis of colorectal cancer." (PMID 36330132, 2022).
myocardial infarction (8 papers, 2015 to 2025). Gross necrosis of the myocardium, as a result of interruption of the blood supply to the area, as in coronary thrombosis. "We discovered that acutely inactivating EglN1 in skeletal muscle decreased heart muscle damage following experimental myocardial infarctions." (PMID 36106637, 2022). "Accordingly, we created mice in which EglN1 was specifically inactivated in the skeletal muscle before experimental myocardial infarctions." (PMID 36106637, 2022).
cervical carcinoma (7 papers, 2013 to 2025). A carcinoma arising from either the exocervical squamous epithelium or the endocervical glandular epithelium. "For instance, EGLN1 overexpression has been associated with poorer survival in cervical squamous cell carcinoma, and knockdown of SLC7A5 has been shown to significantly suppress the migration and invasion capabilities of cervical cancer cells." (PMID 41431124, 2025). "Activated HIF and inhibited EGLN1 regulators suggests a more hypoxic environment in 3D spheroids which may better mimic the known hypoxic environment of HPV+related cervical cancers." (PMID 39193365, 2024). "The activation of HIF and inhibition of EGLN1 suggest a more hypoxic environment in the 3D spheroids, which may better mimic the known hypoxic conditions found in HPV-related cervical cancers." (PMID 39193365, 2024).
glioma (7 papers, 2012 to 2023). A benign or malignant brain and spinal cord tumor that arises from glial cells (astrocytes, oligodendrocytes, ependymal cells). "In fact, Egln3H196A evoked increases in both Klf5 and Oct4 that we speculate may be due to potential dominant-negative effects of Egln3H196A expression within glioma upon other signaling pathways (e.g. Egln1)." (PMID 22905089, 2012). "EGLN1 knockdown comprised the proliferation of IDH1mt astrocyte while downregulating HIF-1α did the opposite; these results suggest that IDHmt-derived D-2HG activates EGLN1, and subsequent downregulation of HIF-1α may lead to the tumorigenesis of glioma." (PMID 33842477, 2021).
pancreatic cancer (7 papers, 2011 to 2024). "Moreover, EGLN1 overexpression may function as a tumor suppressor in pancreatic cancer, which was observed in pancreatic mouse models with decreased tumor growth." (PMID 38928200, 2024). "Our data also shows down regulation of tumour suppressor genes AZGP1, EGLN1 and GNMT of which AZGP1, a Zinc α2-glycoprotein which when silenced was shown to increase invasiveness of pancreatic cancer by induction of mesenchymal transition." (PMID 35854233, 2022).
Sepsis (6 papers, 2016 to 2024). Sepsis is defined as life-threatening organ dysfunction caused by a dysregulated host response to infection. "Survival analysis showed that PRKCD, EGLN1 and CFLAR were positively correlated with sepsis prognosis." (PMID 38997656, 2024).
cholangiocarcinoma (5 papers, 2014 to 2024). A carcinoma that arises from the intrahepatic biliary tree (intrahepatic cholangiocarcinoma) or from the junction, or adjacent to the junction, of the right and left hepatic ducts (hilar cholangiocarcinoma). "The role of the HIF system for HCC pathogenesis is further underlined by mouse studies where HIF-prolyl hydroxylase-2 (PHD2/EGLN1) heterozygous mice displayed more HCC growth and presence of cholangiocarcinoma in response to diethylnitrosamine." (PMID 31083568, 2019).
diabetes (5 papers, 2016 to 2022). "To this end, we inhibited PHD activity, either through pharmacological inhibition, by treatment of the Leprdb/db mice with DMOG or through genetic modification by employing Egln1+/- mice in the STZ-induced model of diabetes." (PMID 35164902, 2022).
leukemia (4 papers, 2022 to 2025). A malignant (clonal) hematologic disorder, involving hematopoietic stem cells and characterized by the presence of primitive or atypical myeloid or lymphoid cells in the bone marrow and the blood. "BCAT1 depletion in leukemia cells leads to the accumulation of α-ketoglutarate, resulting in enhanced Egl nine homolog 1 (EGLN1)-mediated HIF1α degradation." (PMID 35011702, 2022).
pulmonary edema (4 papers, 2014 to 2024). Accumulation of fluid in the lung tissues causing disturbance of the gas exchange that may lead to respiratory failure. "Our prior work had identified the differential distribution of EGLN1 polymorphisms and altered transcription factors on respective loci highlighting the genetic role of EGLN1 on pathophysiological regulations in high-altitude pulmonary edema (HAPE)." (PMID 36180894, 2022). "Another study of the EGLN1 region shows that two polymorphisms within the first intron are found at elevated frequency (71%) in a high-altitude population from India and are associated with EGLN1 expression and high-altitude pulmonary edema (HAPE) in this population." (PMID 24642866, 2014). "Lower DNA methylation of CpG sites in EGLN1 correlated with upregulated plasma EGLN1 levels in high-altitude pulmonary edema." (PMID 38928200, 2024). "On the other hand, the genetic polymorphisms of EGLN1 have been commonly reported to be related to disease development, such as tumor aggressiveness, erythrocytosis, AMS, and HA pulmonary edema." (PMID 35071338, 2021).
atherosclerosis (3 papers, 2017 to 2025). A disease characterized by the build-up of fatty material and calcium deposition in the arterial wall resulting in partial or complete occlusion of the arterial lumen. "HIF1-alpha proteins, which are modulated by EGLN1, are established regulators of inflammation and atherosclerosis." (PMID 29073909, 2017). "Furthermore, EGLN1 blockade was determined to have a beneficial impact on atherosclerosis by reducing approximately 50% of atherosclerotic plaque areas and macrophage numbers in white adipose tissue, increasing autoantibodies against oxidized LDL." (PMID 38649851, 2024). "Similarly, inhibition of EGLN1 has been shown to provide protection against atherosclerosis in mice by improving glucose and lipid metabolism and reducing inflammation and decreasing the areas of atherosclerotic plaque." (PMID 29073909, 2017).
COVID-19 (3 papers, 2024 to 2025). A disease caused by infection with severe acute respiratory syndrome coronavirus 2. "The present study aimed to explore the role of EGLN1 gene variants (rs479200 and rs516651) in COVID-19 severity in the Indian population." (PMID 38291512, 2024). "The present study investigated two single nucleotide polymorphisms (SNPs)—rs479200 and rs516651 in the host EGLN1/PHD2 gene for their association with COVID-19 severity." (PMID 38291512, 2024). "Here, we report a novel finding that the C allele of rs479200 in the EGLN1 gene imparts a high risk of severe COVID-19 (odds ratio—6.214 (1.84–20.99) p = 0.003; 9.421 (2.019–43.957) p = 0.004), in additive inheritance model (adjusted and unadjusted, respectively)." (PMID 38291512, 2024).